TNF (tumor necrosis factor)
Diseases named in the same sentence as TNF in open-access papers (continued):
Sharing a sentence is not in itself a finding about the gene and the disease.
congestive heart failure (continued). "In cell signalling, ET-1 is located downstream of AGEs and upstream of TNF-α, and in chronic heart failure, rats with higher serum levels of ET-1 and TNF-α have reduced heart function and survival." (PMID 36830898, 2023). "In patients with chronic heart failure, LPS responder status, related to the potential to secrete TNF-α to increasing doses of LPS, was an independent predictor of mortality after multivariable adjustment." (PMID 36834796, 2023). "In patients with congestive heart failure, immune cells cultured with lipopolysaccharide secreted high levels of the proinflammatory tumor necrosis factor α, and these levels were significantly reduced in the presence of captopril." (PMID 37725526, 2023). "In patients with chronic heart failure, increased serum levels of inflammatory cytokines, such as IL-6 and TNF-α as well as the soluble adhesion molecules sICAM-1 and sVCAM-1 have repeatedly been detected, suggesting a vascular pro-inflammatory state." (PMID 36979897, 2023). "The ATTACH (anti-TNF Therapy Against Congestive Heart failure) study was prematurely discontinued due to increased mortality in patients with HF on infliximab, a TNF-α antagonist." (PMID 36221014, 2023). "The recommendations provided by clinical practice guidelines state that TNF-alpha inhibitors are relatively contraindicated in patients with congestive heart failure." (PMID 35741329, 2022). "Congestive heart failure is accompanied by increased cytokines like TNF-alpha that propels cardiac cachexia." (PMID 34718902, 2021). "Increased levels of TNF-α and IL-6 are related with the development of congestive heart failure and mortality in patients with congestive heart failure." (PMID 33752661, 2021). "The xanthine-derived drug pentoxifylline has shown to have an immunomodulatory role by inducing the downregulation of TNF-α and other inflammatory cytokines in pulmonary diseases and chronic heart failure." (PMID 34502454, 2021). "In light of this evidence, chronic heart failure is considered a contraindication of anti-TNF-α medications and this represents a strong limitation to their potential use in patients with high cardiovascular risk." (PMID 33770265, 2021). "Nonetheless, studies on the relationship between TNF-α inhibitors and congestive heart failure are contradictory." (PMID 34829740, 2021). "The concentration of proinflammatory cytokines, i.e., TNFα and IL-6 measured in supernatants of human peripheral blood mononuclear cells of a patient with chronic heart failure were inhibited in a dose-dependent manner by furosemide treatment." (PMID 34768805, 2021). "Accordingly, 6 weeks of cycle ergometry reduced sTNFR-II concentrations and maintained TNF-α and IL-6 in elderly patient with chronic heart failure." (PMID 33936044, 2021). "In fact, circulating inflammatory cytokines, such as interleukin-1 beta (IL-1β), IL-6, and tumor necrosis factor alpha (TNFα), correlate with clinical events in patients with chronic heart failure." (PMID 34360595, 2021). "TNFα is one of the key players in the regulation of inflammatory responses and is a drug target in several cardiovascular diseases, including congestive heart failure and coronary artery disease." (PMID 31900413, 2020). "Patients in chronic heart failure also exhibit higher levels of pro-inflammatory cytokines including TNF-α, IL-6, IL-1β, and C-reactive protein." (PMID 32125488, 2020). "This agrees with data from men (57 years old), in a state of increased inflammation due to congestive heart failure (median TNFα concentration: 20.9 pg/mL), vitamin D3 supplementation decreased TNFα (median (IQR): −2.0 (−4.3, 5.5) pg/mL, p = 0.006)." (PMID 29861487, 2018). "It is known that TNF-α is elevated in chronic heart failure patient in accordance with their functional class." (PMID 29487525, 2018). "TNF-α, IL-1β and IL-6 were the main pro-inflammatory cytokines identified as contributors to the syndrome of chronic heart failure." (PMID 29881417, 2018).
congestive heart failure (continued). "The role of inflammation on mitochondrial dysfunction in chronic heart failure seems twofold: IL-6 has been shown to prevent mitochondrial dysfunction in cardiomyocytes, whereas TNF-α induces mitochondrial dysfunction in the same cell type." (PMID 29909553, 2018). "CD 68 is a marker of macrophage infiltration and its presence, along with TNF-α, in heart tissue during chronic heart failure in humans, has been reported." (PMID 29267325, 2017). "Anti-TNF treatment has been tried in patients with congestive cardiac failure, since the high levels of circulating TNF was found in such patients." (PMID 28785220, 2017). "Similar results were observed in a meta-analysis that evaluated of the effects of fish oil supplementation in patients with chronic heart failure, showing that circulating TNFα, IL-1β, and IL-6 decreased after 3 to 12 months of follow-up." (PMID 28599665, 2017). "Other studies also reported that carvedilol can reduce serum TNF production and is able to suppress the CD107a and HLA-DR on circulating cytotoxic T cells, all compounds critical to the pathogenesis of chronic heart failure." (PMID 28377930, 2017). "In a randomized control trial in congestive heart failure patients, vitamin D supplementation significantly reduced the concentration of pro-inflammatory cytokine, TNF-α, with an upregulation in IL-10 levels." (PMID 27271180, 2016). "Proinflammatory mediators such as TNF-α and IL-1ß are important in the pathogenesis of chronic heart failure." (PMID 27195769, 2016). "A link between TNF-signaling and chronic heart failure has been proposed some time ago, although it took a while to translate these findings into a clinical application." (PMID 27435289, 2016). "Previous study indicates that serum TNF-α concentrations of chronic heart failure patients (4.5 ± 0.5 pg/ml) are higher than normal (2.6 ± 0.4 pg/ml)." (PMID 26173590, 2015). "Up-regulation of VCAM-1 and TNF-α has been shown in the cardiac vascular endothelium from patients with chronic heart failure." (PMID 26173590, 2015). "The level of serum TNF-α in congestive heart failure patients was inversely correlated with the number of EPCs in peripheral blood." (PMID 26398523, 2015). "Up-regulation of VCAM-1 and TNF-α has been shown in the cardiac vascular endothelium from the patients with chronic heart failure." (PMID 26173590, 2015). "It was shown that inflammatory mediators, such as IL-6 and tumor necrosis factor - alpha (TNF-α) can activate apoptotic Fas-Fas ligand pathway in chronic heart failure." (PMID 25888309, 2015). "Cardiovascular diseases, including atherosclerotic heart disease, coronary heart disease (CHD), congestive heart-failure (CHF), and other cardiovascular diseases, have been associated with elevated levels of IL-1β, IL-6, TNF-α, and IFN-γ." (PMID 24995360, 2014). "Inflammatory cytokines like tumor necrosis factor alpha (TNF-α) are elevated in congestive heart failure and are known to induce the production of reactive oxygen species as well as to deteriorate respiratory muscle function." (PMID 23300968, 2013). "In a small pilot uncontrolled trial, thalidomide rather increased plasma levels of TNF-α in patients with chronic heart failure, but improved left ventricular function." (PMID 23740214, 2013). "Several experimental studies have demonstrated the role of TNF signaling in myocardial cell apoptosis leading to IR-injury, LV dysfunction and congestive heart failure." (PMID 23405158, 2013). "Amrinone is a type 3 pyridine phosphodiesterase inhibitor used in the treatment of congestive heart failure and is an inhibitor of TNF." (PMID 22432004, 2012). "Vitamin D3 supplementation was found to reduce the proinflammatory cytokine tumor necrosis factor α and enhance the anti-inflammatory interleukin 10, in a cohort of subjects with congestive heart failure." (PMID 23029606, 2012).
congestive heart failure (continued). "Serum level of TNF-α in patients with chronic heart failure increased and correlated with poor cardiac performance." (PMID 22536279, 2012). "Patients with advanced congestive heart failure (New York Heart Association Class III and IV) also showed low IL-10 to TNF-α ratio." (PMID 21949832, 2011). "Vitamin D supplementation of congestive heart failure patients significantly increased serum concentrations of anti-inflammatory cytokine IL-10 and suppressed TNF-α synthesis over a nine month period." (PMID 21600051, 2011). "In patients with chronic heart failure, both TNF-α and Il-6 have been noted to increase in parallel with plasma catecholamines." (PMID 19936283, 2008). "Serum concentrations of TNF-α increased in unsupplemented congestive heart failure patients over a period of 9 months, whereas serum TNF-α concentrations in patients receiving daily supplementation of vitamin D (2000 IU) remained constant." (PMID 18652680, 2008). "Raised levels of TNFα in chronic heart failure, along with the predictive value of high levels of TNFα on adverse outcome in chronic heart failure, led to studies to explore the potential benefit of anti-TNFα therapy in severe chronic heart failure." (PMID 17763428, 2007). "For example, increased plasma TNF-α levels have been shown to induce a faster MHC isoform profile in tibialis anterior muscles from rats with congestive heart failure." (PMID 17678552, 2007). "Additionally, when analysing only patients with chronic heart failure (excluding acute heart failure patients), the Improvement In cardiac function (EF, 6MWT) and Inflammatory markers (IL-6, TNF-α) remained significant, further supporting the findings." (PMID 40951892, 2025). "Similarly, the ATTACH (Anti-TNF-α in Congestive Heart Failure) trial investigating infliximab, a chimeric monoclonal TNF-α antibody, in NYHA III-IV patients highlighted concerns about the safety of TNF-α antagonism in advanced HF." (PMID 40528106, 2025). "TNF-α inhibitors, especially adalimumab and infliximab, are contraindicated in patients with congestive heart failure III/IV and should be cautioned in patients with mild congestive heart failure (New York Heart Association I/II)." (PMID 38029150, 2023). "Abatacept may be used for patients with PsA who respond poorly or intolerant to TNF inhibitors, are complicated with congestive heart failure, or demyelinating disease." (PMID 37485474, 2023). "In cachectic patients with chronic heart failure, plasmatic levels of ghrelin were elevated and were positively correlated with serum levels of GH and TNF-α, suggesting a compensatory mechanism activated in conditions of accentuated catabolism in chronic heart failure." (PMID 36834796, 2023). "The Randomized Etanercept Worldwide Evaluation (RENEWAL) trial combined the results of two trials performed in early 2000s testing efficacy and safety of etanercept, a blocking fusion protein anti-TNF-α, currently employed in the treatment of RA, in patients with chronic heart failure." (PMID 33770265, 2021). "We additionally identified that short-term endurance training at moderate intensities and the combination of endurance, strength, balance, and flexibility training increase plasma IL-10 and reduce plasma IL-6 and TNF-α in healthy elderly adults and male patients with chronic heart failure." (PMID 33936044, 2021). "In addition, the prognostic role of IL-6 and TNF-α in chronic heart failure patients has been demonstrated in previous studies." (PMID 34685378, 2021). "The Anti-TNF Alpha Therapy Against Congestive Heart Failure (ATTACH) trial demonstrated higher rates of HF-related hospitalization or death in the patients with New York Heart Association class III or IV HF receiving infliximab, a TNF alpha inhibitor." (PMID 34660128, 2021).
congestive heart failure (continued). "Moreover, chronic stimulation of TNF can increase the formation of other pro-inflammatory cytokines, such as IL-6 and IL-1, which are also involved in the pathogenesis of Congestive Hearts Failure (CHF)." (PMID 35187113, 2021). "Finally, based on the previous studies, it seems that moderate- to high-intensity endurance training can reduce IL-6 and TNF-α, and increase IL-10 in elderly healthy and patient with chronic heart failure male individuals." (PMID 33936044, 2021). "The role of TNF in congestive heart failure has been commonly accepted." (PMID 29895751, 2018). "Furthermore, in line with our findings, 50 mug/day of vitamin D supplementation for 9 months was able to suppress the production of TNF-α in subjects with congestive heart failure." (PMID 29456507, 2018). "However, TNF inhibitors have restricted applications in some comorbid conditions, such as congestive heart failure, infection, and malignancy." (PMID 27507033, 2016). "Additionally, up-regulation of VCAM-1 and tumor necrosis factor-α (TNF-α) can be detected in the cardiac vascular endothelium of chronic heart failure patients." (PMID 26858641, 2015). "By preventing myocardial hypoxia, ivabradine may diminish the production of cytokines such as IL-6 and TNF-α in congestive heart failure." (PMID 22761780, 2012). "In addition, serum levels as well as the local concentrations of inflammatory cytokines, especially, TNFα, are significantly increased in patients with chronic heart failure and these levels correlate with the degree of functional impairment." (PMID 21453457, 2011). "In addition, an inverse relationship between CYP2C19 activity and plasma TNF-α or IL-6 concentrations has been reported in patients with congestive heart failure." (PMID 18854824, 2008). "Interestingly, n-3 PUFAs supplementation in the form of capsules (2g n-3 PUFAs per day/3 months) significantly decreased IL-6 and TNFα levels in patients with chronic heart failure, and CRP and IL-6 levels were significantly decreased in overweight women with an inflammatory phenotype." (PMID 34440006, 2021). "LPS-mediated TLR4 activation of human coronary artery endothelial cells resulted in increased IL-1β and TNF-α which are elevated in congestive heart failure (CHF) and CAD, hence contributing directly to their pathogenesis." (PMID 32850883, 2020). "Therefore the authors concluded that the stimulus resulting in enhanced plasma concentrations of TNF-α in congestive heart failure remains unclear and concentrations at any particular time were not prognostic." (PMID 27805242, 2016). "Similar results were obtained in a cohort of 105 elderly subjects (mean age 78) with congestive heart failure and hypovitaminosis D, where oral ergocalciferol supplementation was associated with significant variations neither in serum TNF-α levels nor in functional outcomes after 10 weeks." (PMID 27043616, 2016). "The low frequency of anti-TNF utilization, and, thereby, greater use of systemic steroids, may be partly attributable to higher rates of anti-TNF contraindications (decompensated congestive heart failure (CHF), malignancies) in older patients compared to their younger counterparts." (PMID 26643112, 2015). "Adipose tissue in obese patients produces tumor necrosis factor-α (TNF-α) receptors, neutralizing TNF-α’s adverse effects in acute and chronic heart failure." (PMID 40150180, 2025). "Donepezil administration in CHF rats has been shown to reduce pro-inflammatory markers, like TNF-α, indicating the connection between the beneficial effects of AChE inhibitors and CAP in chronic heart failure." (PMID 40725139, 2025). "Proinflammatory cytokines such as IL-1α, IL-1β, TNF-α, and TNFR2 are elevated in animal models and patients with chronic heart failure." (PMID 40072051, 2025).
congestive heart failure (continued). "In a study involving 72 patients with chronic heart failure (CHF), Astragalus injection significantly reduced inflammatory cytokines, including tumor necrosis factor-alpha (TNF-α) and IL-6, in elderly CHF patients." (PMID 40276608, 2025). "In rats with chronic heart failure (CHF), nine inflammatory factors were detected in the SG, and TNF-α and IL-1β levels were increased." (PMID 39328238, 2024). "For instance, the systemic administration of anti-TNFα presents certain risks such as the reactivation of latent tuberculosis and in the case of IFX, it is contraindicated in patients suffering from congestive heart failure." (PMID 36986627, 2023). "Additionally, multiple studies have shown that as a result of chronic heart failure, the peripheral circulation and the heart are characterized by intense inflammatory responses, with significant elevations of pro-inflammatory cytokines, including TNF-α, IL-1β, and IL-6." (PMID 36361807, 2022). "A large amount of evidence shows that long-term abnormal changes in inflammatory cells such as macrophages and immune molecules such as tumor necrosis factor-α (TNF-α) can promote the development of myocardial fibrosis and chronic heart failure." (PMID 36312232, 2022). "This is a phosphodiesterase inhibitor with the capacity to inhibit TNF-α, already approved by FDA to treat congestive heart failure." (PMID 34832866, 2021). "The ATTACH (Anti-TNF Therapy Against Congestive Heart Failure) (n = 150) and RENEWAL (Randomized Etanercept Worldwide Evaluation) (n = 2048) trials investigated TNF-α antagonism in moderate-to-severe HFrEF." (PMID 31963368, 2020). "First of all, high tumor necrosis factor (TNF)-alpha, Interleukin (IL)-1-alpha and IL-1-beta were detected in the plasma of myocarditis patients with congestive heart failure." (PMID 29245918, 2017). "In clinical settings, QSYQ can improve cardiac function through anti-inflammatory effects by reducing TNF-α and IL-6 levels both in AMI and chronic heart failure patients." (PMID 24817581, 2014). "An inverse relationship between plasma cytokine (TNF-α and IL-6) concentrations and CYP2C19 activity has been demonstrated in patients with congestive heart failure." (PMID 18854824, 2008). "Tumor necrosis factor-α (TNF-α), IL-6, and IL-1 have all been observed to be elevated in both humans and animal models of chronic heart failure." (PMID 19936283, 2008). "It is also noteworthy that in patients with chronic heart failure, there are macrophages that expressed TNFα, which were not present in control patients." (PMID 38256155, 2024). "Chlorzoxazone has negative correlation with plasma TNF and IL‐6 levels in patients with congestive heart failure." (PMID 36988255, 2023). "hsCRP: high sensitivity C-reactive protein; NLR: Neutrophil Lymphocyte Ratio; VTE: Venous Thromboembolism; MVO: Microvascular Obstruction; WBC: White Blood Cells; CRP: C-reactive protein; CHF: Congestive Heart Failure; USA: United States of America; TNF-α: Tumor Necrosis Factor-alpha." (PMID 37859889, 2023). "In a study that used a walking intervention for chronic heart failure patients for four days in the forest, there was a significant change seen in IL-6 levels, but no significant change was reported in TNF-α levels." (PMID 34444188, 2021). "Large clinicals trials evaluating TNF-α inhibitors in HF (Randomised Etanercept Worldwide Evaluation (RENEWAL), Anti-TNF Therapy Against Congestive Heart Failure (ATTACH)) have yielded dissatisfactory results and further testing of TNF-α inhibitors in patients seems currently unlikely." (PMID 32937823, 2020). "Specifically, elevated levels of TNF-α and soluble TNF receptors have been found in lesional psoriatic skin and in the serum of patients with severe Pso, which similarly reflect those detected in congestive heart failure (CHF) patients." (PMID 30150978, 2018).